IL10 (interleukin 10)
Diseases named in the same sentence as IL10 in open-access papers (continued):
Sharing a sentence is not in itself a finding about the gene and the disease.
infection (continued). "Four weeks post-infection, a real-time PCR analysis of inflammatory gene expression revealed that purified macrophages from infected WT mice exhibited enhanced IL-10, Arg-1, MCP-1, RELMa, and IL-6 but reduced TNF-α, IL-12, and iNOS mRNA levels, which exhibited an M2 dominant- polarized phenotype." (PMID 30589840, 2018). "Therefore, CD4 T cells (CellTrace Violet+) from IL-10 KO mice 7 days post-infection (p.i.)were adoptively transferred into infection-matched IL-10 KO recipients, which underwent transcardial perfusion and brain tissue collection 3.5 h later." (PMID 29866139, 2018). "In addition, pharmacological inhibition of sphK1 by DMS have been shown to exacerbate the infection by increasing disease promoting ERK1/2 induced IL-10 secretion, while on the other hand, decreasing p38 activated IL-12 production." (PMID 30118478, 2018). "Higher numbers of IL-10 producing CD4+ cells together with increased Treg cell numbers supports participation of these immune responses in suppression of excessive inflammation during simultaneous infection by B. burgdorferi and B. microti in C3H mice." (PMID 30619263, 2018). "However, GSK3α activity inhibition at later stages of infection favors CREB activation that leads to IL-10 expression." (PMID 29434603, 2018). "Therefore, in response to infections, females usually activate Th2 responses and produce high levels of interleukins (IL) IL-4, IL-5, and IL-10." (PMID 29925409, 2018). "To note, the anti-inflammatory cytokine IL-10 is also increased after H3 and T1 infection." (PMID 29795378, 2018). "A potential pathophysiological pathway is overproduction of IL-10 during infection with C. burnetii, which could play a role in the development of B-cell NHL." (PMID 28840502, 2018). "The necessity of Tfh-derived IL-10 in maintaining humoral immunity during LCMV Cl13 infection raised the question as to whether IL-10 is acting in an intrinsic manner on either Tfh cells themselves, or on B cells to reinforce the GC reaction." (PMID 30487586, 2018). "However, significantly high (P = 0.01) level of IL-10 was observed in children who have acquired infection than those free from infection even born to infected mother." (PMID 30252839, 2018). "We show that CD4 IL10 production is associated with high-parasite antigen burden, consistent with other infections as well as non-infectious disease models." (PMID 29097996, 2017). "Interestingly, polyclonal B cell activation accompanies many types of infections and results in the expansion of IL-10-releasing B cells." (PMID 29403470, 2017). "We observed that butyrate-treated mice challenged with C. rodentium showed differing increases in gene expression of cytokines involved in the clearance of infection (Il17A, Tnfα), the reduction of mucosal inflammation (Tgfβ, Il10), and the improvement of host barrier function (Muc2, Relmβ, Tff3)." (PMID 28861518, 2017). "Considering the role of Mincle in regulating IL-10 production, it would be interesting to analyze whether inhibition of IL-10 at the same time of vaccination using TDB as an adjuvant can increase protection to the respective infections." (PMID 28791019, 2017). "S. epidermidis seems to trigger low levels of pro-inflammatory cytokines secretion and high levels of IL-10, which may contribute to the sub-acute nature and persistence of the infection." (PMID 28824556, 2017). "Early studies using IL-10–deficient mice were inconclusive about the functional role of IL-10 during M. tuberculosis infection, but more recent studies have shown that IL-10 plays a detrimental role during infection by limiting host-protective immune responses." (PMID 28584007, 2017). "For this purpose we treated C57BL/6 WT mice with endogenous IL-10 prior to infection." (PMID 28686630, 2017). "Thus, it is likely that IL-10 treated macrophages have difficulties in controlling infection with the intracellular bacterium B. pseudomallei due to insufficient phagolysosome function." (PMID 28686630, 2017).
infection (continued). "In particular, it has also been reported that the infection of BCG or Mtb into DCs could lead to enhanced secretion of immune regulatory IL-10 via TLR2-dependent ERK activation, reciprocally suppressing IL-12 secretion." (PMID 29123166, 2017). "Other cell types represented only minor sources of IL-10 throughout infection." (PMID 28584007, 2017). "From these analyses we conclude that H. diminuta and T. muris antigens can trigger an early pro-inflammatory response with increased TNF-α both in the absence and presence of Mtb-infection which is then shifted towards an anti-inflammatory response with a synergistic increase of IL-10." (PMID 28192437, 2017). "Previous studies have demonstrated the production of interferon-gamma (IFN-γ), interleukin 12 (IL-12), nitric oxide (NO) and tumour necrosis factor alpha (TNF-α) in early stages of infection and later interleukin 13 (IL-13), interleukin 4 (IL-4) and interleukin 10 (IL-10)." (PMID 28655350, 2017). "However, overexpression of TGF-β or IL-10 very early in infection inhibits the pro-inflammatory response and impedes parasite clearance." (PMID 28337195, 2017). "Interestingly, IL-10 increased significantly only in infected pregnant mice (p = 0.02) suggesting a robust regulatory response to infection." (PMID 29176767, 2017). "However, in our experimental settings, we observed that the production of IL-10 by these cells cannot fully reverse the resistant of IL-10−/− mice to the infection." (PMID 28824622, 2017). "However, there was a marked increase in the amount of Il10 mRNA 5 days after infection in both caecum and colon, whereas mRNA levels of the pro-inflammatory cytokines IL-6 and TNFα were unchanged or moderately increased, respectively." (PMID 29241040, 2017). "We also measured cytokine production after C. albicans restimulation of splenocytes obtained from 2-DG or BPTES-treated mice after the infection, finding a significant reduction in the production capacity of IL-1β, IL-6, IL-10, TNFα and IFNγ in mice treated with 2-DG." (PMID 28922415, 2017). "Importantly, we observed a high level of serum IFN-γ in infected IL-10−/− mice at 5 days of infection, which is a cytokine important for the elimination of intracellular S. Typhimurium." (PMID 28824622, 2017). "While recent evidence suggests that the production of IL-10 from T cells may be crucial in switching from innate to adaptive immunity during infection and lesser production may be connected to enhanced morbidity in young populations." (PMID 28270815, 2017). "Monocytes were the major innate population of IL-10+ cells present in the lung after M. tuberculosis infection, whereas macrophages, DCs, and NK cells constituted a minor proportion of IL-10–expressing cells throughout infection." (PMID 28584007, 2017). "Thus, caspase-6 seems to affect the expression of IL-10 and IL-1β in a very early stage after infection." (PMID 28686630, 2017). "However, NK cells can also produce IL-10 during L. donovani infection, suggesting they can play either antiparasitic or immunoregulatory roles during infection." (PMID 29167671, 2017). "Our results also suggest that IL-10 could be acting on the IFN-γ or other cytokines involved in protective mechanisms in infection with T. cruzi strains." (PMID 29255475, 2017). "The regulatory cytokine IL-10 is also present in vivo and it has been shown that S. epidermidis inoculation result in higher IL-10 levels compared to P. aeruginosa in an intradermal infection model." (PMID 28824556, 2017). "The immunostimulatory effects of [G11k,N15K]alyteserin-2a, esculentin-2CHa and pseudhymenochirins 1Pb and 2Pa on peritoneal macrophages are complemented by the inhibition of anti-inflammatory IL-10 production, indicating a possible role in ameliorating the innate immune response during infection." (PMID 29236056, 2017). "The IFN-γ/IL-10 ratio is a good indicator of infection resolution both in vitro and in vivo." (PMID 28553635, 2017).
infection (continued). "Infection with the other two Curvularia strains did not cause significant change in the IL-8 and IL-10 level." (PMID 29093719, 2017). "In our experimental settings, the sole transfer of IL-10 producing DCs and BM macrophages did not restore the ability of S. Typhimurium to cause a systemic and lethal infection in IL-10−/− mice." (PMID 28824622, 2017). "Notably, polymorphisms in the promoter region of IL-10 are thought to be associated with various diseases, the outcome of both HCV and HIV-1 infection." (PMID 28910419, 2017). "We conclude that Nod2 signaling is required for the fine-tuned innate and adaptive local (i.e., intestinal) and systemic immune responses upon C. jejuni infection of secondary abiotic IL-10−/− mice, but does not limit pathogenic infection." (PMID 28752081, 2017). "IL-6, IL-8, and IL-10 circulating levels were shown to be higher in cases of infection." (PMID 28148470, 2017). "Anti-inflammatory IL-10 was overall downregulated with infection." (PMID 29348965, 2017). "The lowest level of IL-10 production after infection was observed in T cells." (PMID 28824622, 2017). "Besides Tregs, the cytokine IL-10 was identified as key immunoregulator during infection with different pathogens including Plasmodium ssp." (PMID 28293237, 2017). "In addition, the bacterial load in spleens and livers from IL-10 treated animals were significantly higher at 48 hours after infection." (PMID 28686630, 2017). "Other studies showed that BNZ could modulate the synthesis of IL-10, altering the balance of cytokines and changing the course of infection." (PMID 29255475, 2017). "Furthermore, infected children had more phenotypically exhausted PD-1+ CD4+ T cells, more Tregs expressing TNF-RII, and higher IL-10 responses to PfRBCs, which persisted following resolution of infection." (PMID 28821806, 2017). "At 3 dpi, the levels of IFN-γ, IL-6, IL-10, MCP-1, and TNF-α in BALB/c mice infected with MA/12 were considerably higher than in animals inoculated with PH/13 or BR/08; however, only the IL-10 elevation was significant (P < 0.05) relative to that observed with PH/13 infection." (PMID 28779075, 2017). "It is important to mention that, in our study, we observed a peak of IL-10 production at 5 days of infection, which agrees with the idea that the main producer of IL-10 are adaptive immune cells, or even by other innate immune cells that respond to signals provided by these adaptive immune cells." (PMID 28824622, 2017). "IL-10 levels in control/A(H1N1)pdm09 mice increased to 202.4 pg/mL at 7 days post-infection." (PMID 28831046, 2017). "Because IFNγ/IL10 CD4 T-cell responses have been associated with high antigen burden in other systems, we assessed the relationship of Pf–specific responses and parasite density during the most recent infection (within 3 months prior to blood draw)." (PMID 29097996, 2017). "IL-10 levels were undetectable in all mice until 3 days post-infection." (PMID 28831046, 2017). "Ethanol treatment significantly reduced IL-10 cytokine release 48 hours after infection." (PMID 29348965, 2017). "Despite healing of cutaneous lesions, parasites continue to persist at the original site of infection, in part due to IL-10-mediated mechanisms, and these persisting parasites are thought to help maintain effector memory CD4+ T cells (TEM) that protect against re-infection." (PMID 29167671, 2017). "Effector CD8+ T cells can produce IL-10 during the acute phase of influenza virus, respiratory syncytial virus, coronavirus infection, paramyxovirus simian virus 5, or vaccinia infections." (PMID 28316998, 2017).
infection (continued). "However, a significant increase in IL-1α and IL-10 levels was observed in LP infected animals due to the interaction between protein malnutrition and infection (p < 0.05)." (PMID 28397794, 2017). "IL-10 is an anti-inflammatory cytokine and a key immunoregulator during infection." (PMID 29089927, 2017). "A CSF pro-inflammatory response consists of an interplay of Th1 (IFN-γ and IL‐6), Th2 (IL‐4 and IL‐10) and Th17 cytokines (IL‐17A) and has been shown to be highly predictive of increased macrophage activation, rapid clearance of infection and consequently better survival in patients with CM." (PMID 28486489, 2017). "Whereas we observed significantly elevated percentages of IL-10-expressing CD11c+CD11b+CD8− DCs in the course of infection, the frequency of IL-10+ CD11c+CD11b−CD8+ DCs was reduced at day 5 postinfection but recovered to levels of non-infected mice at day 7, 10, and 14 postinfection." (PMID 28293237, 2017). "Furthermore, IL-10-secreting B cells were described in different types of infection including polyclonal B cell expansion triggered by Staphylococcus aureus, HIV patients, and murine schistosomiasis models." (PMID 29403470, 2017). "Furthermore, IL-10 induces Treg cell proliferation, promoting an equilibrated immune response that control pathogen infection, altogether reducing excessive inflammatory damage to the affected tissues." (PMID 28824622, 2017). "Colonic mucin-2 mRNA was, however, down-regulated upon C. jejuni-infection of both Nod2−/− IL-10−/− and IL-10−/− mice, whereas expression levels were lower in infected, but also naive Nod2−/− IL-10−/− mice as compared to respective IL-10−/− controls." (PMID 28752081, 2017). "IL-10 is an anti-inflammatory cytokine, which can act as a feedback regulator of Th1 and Th2 cell responses during infection, as well as suppresses IL-12 production in DCs and macrophages leading to a block in the development of Th1-type responses, compromising pathogen clearance." (PMID 28264048, 2017). "Conversely, innate as well as adaptive immune cells such as macrophages and monocytes as well as T lymphocytes and regulatory T-cells, respectively, were even more abundant in large intestines of Nod2−/− IL-10−/− as compared to IL-10−/− mice at day 7 post-infection." (PMID 28752081, 2017). "Recently, it was demonstrated that IL-10 is exclusively produced by T cells and not by macrophage, and granulocytes are associated to pathogenesis in infections caused by L. mexicana." (PMID 28848541, 2017). "Moreover, blocking IL-10 activity in the course of infection leads to the overproduction of proinflammatory mediators." (PMID 29285277, 2017). "Although it is still unclear whether IL-27 also regulates IL-10 expression by T cells during M. tuberculosis infection, IL-27Rα signaling in CD4+ T cells has been recently shown to confer susceptibility to this infection." (PMID 28584007, 2017). "In contrast, IL-10 had 92.9% sensitivity for detecting patients with microbiologically documented infection and the NPV was 95.2; therefore, IL-10 may be a useful marker for ruling out culture-confirmed infection." (PMID 28148470, 2017). "Importantly, we observed that among the cytokines tested in this study at 5 days of infection, the only one that was elevated in the serum of infected mice was IL-10." (PMID 28824622, 2017). "Similar results were obtained when mice treated between days -1 and 3 p.i. with αIL-6 were infected with mouse adapted H1N1 IAV PR8 (strain A/Puerto Rico/8/1934 H1N1), with IL-6 depleted mice showing delayed recovery from infection and reduced IL-6, IL-10 and IL-27 in the airways at day 10 p.i.." (PMID 28953978, 2017). "The ability of LANCL2 activation to promote a regulatory, IL-10-producing, macrophage population suggests efficacy of this pathway to control the damaging effects of the influenza virus in the lungs throughout the course of infection." (PMID 28270815, 2017).
infection (continued). "After infection, mice were administered an IL-10 neutralizing antibody or isotype control." (PMID 28270815, 2017). "This suggests that, while MDSCs may assist in the resolution of infection, IL-10-producing cells are the critical effectors of NSC61610 treatment and LANCL2 activation." (PMID 28270815, 2017). "At 48 h after infection, the results were similar for both IL-4 and IL-10." (PMID 28767981, 2017). "Prior to experimental infection, during an undefined transient infection (as evidence by an IL10 response), the authors noticed that, compared to calves that received multiple skin tests, control animals appeared to have higher proliferative responses and IFN-γ synthesis." (PMID 29109952, 2017). "In vivo IL-10 level was raised 5 wk post infection by IVCCA assay." (PMID 28614408, 2017). "The results showed that the expressions of TNF-α, IL-12, IL-5, IL-10 and GM-CSF in serum increased from five weeks post-infection and to peak levels at week 6 post-infection; however, as typical type 1 cytokines, the levels of IL-2 and IFN-γ in serum did not change during the key period." (PMID 28539607, 2017). "In mice, IL-10 and TGFβ have been implicated as factors promoting the persistence of L. (L.) tropica long after the initial infection subsides, but a role for these cytokines in human LR has not been documented." (PMID 28629171, 2017). "IL-1β, IL-10, KC, and G-CSF levels were all induced by infection." (PMID 28672877, 2017). "We infected human (THP-1) or mice macrophages (MHS) at MOI 1:1 for 1 h with either the wild type H37Rv, the Δpmt mutant, and the Rv1002c-complemented strain and assayed inflammatory (TNF-α) or anti-inflammatory (IL-10) cytokines at 5, 24 and 48 h post-infection." (PMID 28801649, 2017). "Moreover, whereas Ag-experienced CD4+ T cells obtained on day 60 of infection produced only marginally less IFN-γ, they produced significantly less IL-10 than did counterpart cells obtained from day 7 of infection." (PMID 27630165, 2016). "We compared the expression profile of Th1 (IFNγ) and Th2-associated (IL-4 and IL-10) mRNAs in dLNs of WT and CatB-/- mice during infection since we found no detectable transcripts in the FPs." (PMID 27182703, 2016). "Moreover, in a Pseudomonas aeruginosa intranasal infection model, this immunomodulatory effect towards IL-10 secretion seems to be mediated by EP2 since EP2-/- mice presented a lower bacterial burden in the lung." (PMID 28018318, 2016). "Combined with our data, it is reasonable to postulate that the DENV-ADE infection may suppress the cellular antiviral response by suppressing not only early induction of ISGs but also the later IFN signalling with IL-10 or IL-6." (PMID 26923481, 2016). "Our results suggest an association between increased IL-6 and IL-10 levels and stages of infection pre-HAART, independent of the slow or rapid progression status of the patient." (PMID 27214135, 2016). "TNF-α/IL10 plasma ratio measured shortly after burn trauma was inversely correlated with burn size and the injury severity scores investigated, and was predictive of repeated infections (≥3 infection episodes) outcome (AUROC [95%CI] of 0.80 [0.63–0.93])." (PMID 27761434, 2016). "There has been controversy over whether direct productive infection of the DC is required to generate its IL-10 production." (PMID 26808628, 2016). "Therefore, although IL-4RαKO and RelmαKO mice produce similar amounts of IL-4 after 1x and 4x infections, IL-4RαKO mice have a more pro-inflammatory phenotype (i.e. increased IL-12p40) and both KO strains had decreased IL-10 production compared to WT mice." (PMID 27505056, 2016). "From these observations we predict that early priming of the fetal immune system by filarial antigens modulate the development of Tregs, which ultimately scale up the production of IL-10 in neonates and creates a milieu for high rate of acquisition of infection in children born to infected mothers." (PMID 27861499, 2016).